GATA2 (GATA binding protein 2)
Diseases named in the same sentence as GATA2 in open-access papers (continued):
Sharing a sentence is not in itself a finding about the gene and the disease.
Fanconi anemia (13 papers, 2017 to 2025). Fanconi anemia (FA) is a hereditary DNA repair disorder characterized by progressive pancytopenia with bone marrow failure, variable congenital malformations and predisposition to develop hematological or solid tumors. "Inherited predisposition syndromes (e.g., Li–Fraumeni, Fanconi anemia, GATA2 deficiency) as well as somatic conditions like clonal hematopoiesis of indeterminate potential (CHIP) offer opportunities for early surveillance or preventive interventions." (PMID 40722725, 2025). "A CBC as a follow-up should be performed every six months for patients and family members at risk that carry RUNX1, GATA2 or Fanconi anemia pathogenic variants." (PMID 34057692, 2021). "At our single institution, we had a yield of 14% (6/43) for patients with MDS or AML who were found to have a PV predisposing to myeloid disease (Fanconi Anemia, DKC1, DDX41, GATA2, TERC, and RUNX1)." (PMID 40936482, 2025). "In this study, a diagnosis of Fanconi anemia was made in a patient with unclassified IBMFSs and a diagnosis of GATA2-related disorder in another with idiopathic MDS." (PMID 31839986, 2019). "Patients with Diamond–Blackfan anemia, Fanconi anemia, dyskeratosis congenita, and familial thrombocytopenia/AML and MDS predisposition syndromes due to RUNX1, ANKRD26 gene mutations, and GATA2-associated MDS/AML met these criteria." (PMID 28690869, 2017). "When transplanting before transformation to MDS, non-myeloablative regimens similar to the ones used for Fanconi’s anemia or GATA2 deficiency syndrome can probably be used, even though evidence for this assumption are missing at the moment." (PMID 29535429, 2018). "However, the patients primarily harbored GATA2 variants, and no patients with classical bone marrow failure syndrome (such as Fanconi anemia) were identified." (PMID 38137719, 2023).
viral infections (13 papers, 2014 to 2025). "While severe viral infections are significantly more common in persons with GATA2 null mutations, these infections were also associated with missense and regulatory mutations." (PMID 29375553, 2017). "It has been shown that the inability to confine viral infections in patients with GATA-2 deficiency correlates well with the extent of cytopenias, namely with the lack of DC-, NK- and CD4pos T-cells." (PMID 25879889, 2015). "Notably, solid tumors associated with GATA2 deficiency are linked to underlying viral infections, particularly HPV and EBV." (PMID 39981594, 2025). "GATA2 deficiency presents with multi-lineage cytopenia, mycobacterial, fungal and viral infections." (PMID 31035956, 2019). "Associated with transcriptionally regulatory network, ISG15 expression which was targeted by STAT5B and GATA2 factors was induced by virus infection." (PMID 25907774, 2015). "In addition, other IEIs affecting innate and/or adaptive immune cells and predisposing to multiple viral and non-viral infections may result in severe EBV infection, including mutations in GATA2, MCM4, FCGR3A, CARD11, ATM, and WAS." (PMID 36980798, 2023).
bone marrow failure syndrome (11 papers, 2016 to 2025). "GATA2 deficiency is linked to multiple clinical manifestations, such as increased susceptibility to infections, hematological malignancies, and bone marrow failure syndrome." (PMID 41154393, 2025). "GATA2 deficiency resembles other inherited bone marrow failure syndromes in terms of high rates of transplant-related toxicity/mortality (TRT/TRM) after myeloablative regimens, due to cellular defects." (PMID 40299403, 2025). "MDS with monosomy 7 frequently occurs in patients with germline variants in GATA-binding factor 2 (GATA2), sterile alpha motif domain containing 9 (SAMD9), sterile alpha motif domain containing 9 like (SAMD9L), or hereditary bone marrow failure syndrome." (PMID 38203823, 2024).
Obesity (11 papers, 2015 to 2025). Accumulation of substantial excess body fat. "Defective GATA-2 expression regulates adipocyte differentiation through molecular control of the preadipocyte-adipocyte transition, which is associated with obesity." (PMID 37398946, 2023). "Moreover, obesity can be a cause of elevated bST, as well as helminthic infections, hematological malignancies, cardiovascular disease, (nummular) eczema, or rare genetic mutations (e.g., GATA2 or PLAID)." (PMID 38132246, 2023). "Consequently, defective GATA2 and GATA3 expression is associated with obesity, while expression of GATA2 and GATA3 inhibits adipogenesis and traps cells at the preadipocyte stage, which could be as a result of direct suppression of PPARγ." (PMID 26797605, 2016). "The Obesity TRFs GATA2 and TCF4 were predicted to interact with four and two interactors, respectively." (PMID 40102990, 2025). "They concluded their study that GATA2 can be a new target in preventing and treating obesity-related inflammation and its complications." (PMID 38956704, 2024). "Their variants affect the obesity risk by modulating the binding affinity of obesity-related transcription factors, such as STAT3, CEBPB, TCF7L2, FTO, and GATA2, and changing the phosphorylation of proteins, such as BDNF with the rs6265 risk allele." (PMID 34836030, 2021). "In the obesity signature, eight genes were found to possess regulatory functions: COPS5, GATA2, MORF4L1, OPTN, PFDN5, SETBP1, TCF4, and ZBTB16." (PMID 40102990, 2025). "When we investigated the list of 162 DMRs mapping to annotated loci in further detail we observed other genes with known and potential roles in obesity and related traits (such as PRKCZ, NDUFS2, GATA2, FOXP2, ANGPT2, NCOR2, CPT1B, PTPN6)." (PMID 25651499, 2015).
aplastic anemia (10 papers, 2012 to 2026). Anemia resulting from bone marrow failure (aplastic or hypoplastic bone marrow). "Expression of GATA-2 mRNA in purified CD34-positive cells was significantly decreased in aplastic anemia compared with normal subjects when examined by immunocytochemical analysis." (PMID 25619630, 2015). "GATA2, located on 3q21 11 is pivotal in proliferation of hematopoietic stem cells (HSC) and mutations were first described in aplastic anemia 12–15." (PMID 25619630, 2015). "Although GATA-2 expression was reported to be decreased in CD34-positive cells in aplastic anemia, many questions remain regarding the intrinsic characteristics of hematopoietic stem cells in this disease." (PMID 23028422, 2012). "Analyzing bone marrow and peripheral blood in flow cytometry, the most distinctive feature of GATA2-related MDS seems to be the reduction of B cells, compared to healthy controls, aplastic anemia, and MDS patients without GATA2 deficiency." (PMID 33066218, 2020). "Germline GATA2 mutations were found in 7% of primary MDS cases, 15% of advanced MDS, and were never found in children with MDS secondary to aplastic anemia or previous cancer therapy." (PMID 33066218, 2020). "Our results suggested that GATA-2 directly regulates HOXB4 expression in hematopoietic stem cells, which may play an important role in the development and/or progression of aplastic anemia." (PMID 23028422, 2012). "Furthermore, we assessed GATA-2 and HOXB4 expression in CD34-positive cells from patients with aplastic anemia (n = 10) and idiopathic thrombocytopenic purpura (n = 13), and demonstrated that the expression levels of HOXB4 and GATA-2 were correlated in these populations (r = 0.6573, p<0.01)." (PMID 23028422, 2012).
gastric cancer (10 papers, 2017 to 2024). A primary or metastatic malignant neoplasm involving the stomach. "It has been reported that aberrant DNA methylation on GATA2 affects GATA6 expression levels in gastric cancer progression." (PMID 33579350, 2021). "Abnormal GATA2 epigenetic dysregulation can induce unfavorable phenotypes in human gastric cancer by decreasing expression of GATA6, which has a vital role in gastrointestinal development." (PMID 34539736, 2021). "MiR-451 was downregulated in gastric cancer, and its proved target were GATA2, ABCB1, MIF." (PMID 30736753, 2019). "For example, GATA2 was suggested as a prospective indicator for poor prognosis in patients with colorectal cancer, and FAT4 functions as a tumor suppressor for stomach cancer." (PMID 29299064, 2017).
chronic granulomatous disease (9 papers, 2018 to 2023). Chronic granulomatous disease (CGD) is a rare primary immunodeficiency, mainly affecting phagocytes, which is characterized by an increased susceptibility to severe and recurrent bacterial and fungal infections, along with the development of granulomas. "Occasional cases have been associated with immune disorders such as GATA2 deficiency, Job’s syndrome, chronic granulomatous disease (CGD), X-linked CD40 ligand deficiencies, and sporadic monocytopenia." (PMID 38003768, 2023). "Among the genetic disorders associated with these aspergillosis syndromes, ABPA is primarily seen with CFTR mutations, while IA and CPA are largely seen in chronic granulomatous disease (CGD), autosomal dominant hyper-IgE (Job’s) syndrome, GATA2 deficiency, and CARD9 deficiency." (PMID 36986378, 2023). "Classical PIDs, such as combined immunodeficiency (CID) and severe combined immunodeficiency (SCID), chronic granulomatous disease (CGD) and GATA2 deficiency, are associated with increased susceptibility to diseases caused by diverse infectious pathogens, including mycobacteria." (PMID 36338958, 2022). "The fatal outcome of BCG disseminated infection has also been reported in other PID less prone to BCG infection, such as chronic granulomatous diseases (CGD), hyper-IgE syndrome (HIES), X-linked hyper IGM syndrome (HIGM), nuclear factor (NF)-κB essential modifier (Nemo), and GATA2 deficiency." (PMID 31749033, 2020).
chronic myeloid leukemia (9 papers, 2014 to 2025). "Here, we report that Gata2-L359V mutation impeded hematopoietic differentiation in murine embryonic and adult hematopoiesis and blocked murine chronic myeloid leukemia (CML) cell differentiation." (PMID 34078881, 2021). "Two mutations in the coding region (zinc finger domain) of Gata2 have been identified in a subset of human chronic myelogenous leukemia (CML)." (PMID 34195082, 2021). "GATA2 also plays a role in other hematopoietic malignancies with the acquisition of neomorphic mutations in the second zinc finger of GATA2 resulting in poorer outcomes in patients with chronic myeloid leukemia." (PMID 34589480, 2021). "GATA2 mutations are identified in MDS in blast crisis of chronic myeloid leukemia (CML)." (PMID 32188030, 2020). "For example, pathogenic or likely pathogenic alleles in GATA2, ASXL1, or TET2 were found in 10% of pediatric chronic myeloid leukemia cases, with additional putative risk alleles in another 60%." (PMID 41010648, 2025). "A recent study used CRISPR to validate the importance of a SE near GATA2 in chronic myeloid leukemia by demonstrating it is responsible for 80% of GATA2 expression." (PMID 25486255, 2014). "Rps19_Neu, Anxa1_Neu and Classical_Neu had high specificity in the atypical chronic myeloid leukemia, but they were not expressed in GATA2 deficiency." (PMID 38319415, 2024).
colorectal cancer (8 papers, 2015 to 2024). A primary or metastatic malignant neoplasm that affects the colon or rectum. "Our previous studies suggested that high GATA2 expression is associated with recurrence of colorectal cancer (CRC)." (PMID 26287967, 2015). "GATA2 is highly expressed in colorectal cancer cells and serves a prognostic factor." (PMID 38632500, 2024). "Comparison of mRNA levels in a GC data set from the NCBI’s Gene Expression Omnibus (GEO) also revealed positive correlations among CGA, EGFR, and GATA2; intriguingly, positive correlations also were observed in a similar analysis of the GEO colorectal cancer (CRC) data set." (PMID 35289315, 2022).
coronary artery disease (8 papers, 2006 to 2023). "The TF GATA2 expression is high in the thoracic aorta and GATA2 variants are associated with early‐onset familial coronary artery disease." (PMID 32196466, 2020). "Previous genetic linkage studies have shown that single nucleotide polymorphisms (SNPs) in GATA2 are associated with coronary artery disease and diabetes." (PMID 33193444, 2020). "Of the transcription factors upregulate in IIMs, only GATA2 had been previously implicated in coronary artery disease in humans." (PMID 33193444, 2020). "The relevance of its increased transcription in CD34+ cells in CAD patients is underscored by the association of a polymorphisms in GATA2 with familial early onset coronary artery disease." (PMID 20565948, 2010). "These GATA2 target genes, which remain to be explored in this context, represent a rich set of candidate genes from which to dissect genetic contributions to coronary disease susceptibility." (PMID 16934006, 2006). "GATA2 has been identified as a novel gene for coronary artery disease risk, and research on this transcription factor and its downstream effector may reveal a regulatory network crucial for the generation of coronary artery disease." (PMID 37684436, 2023). "The GATA2 gene maps beneath the Chromosome 3q linkage peak from our family-based sample set (GENECARD) study of early-onset coronary artery disease." (PMID 16934006, 2006). "Polymorphic gene GATA2 has been reported to be crucial for the progression of coronary artery disease, but this gene might be responsible for advancement of T1D in patients with coronary artery disease." (PMID 33827531, 2021). "However, CDKN2B-AS was involved in the pathogenesis of coronary artery disease by targeting miR-92a-3p through GATA2, MAP1B and ARG1 regulation." (PMID 29552296, 2018).
hepatocellular carcinoma (8 papers, 2014 to 2024). A malignant tumor that arises from hepatocytes. "Except hepatocellular carcinoma, high levels of GATA2 expression indicate tumor recurrence, metastasis, or poor survival." (PMID 26287967, 2015). "However, further experiments are needed to address how does liver gain ectopic expression of hematopoietic factor GATA2 with concomitant loss of endoderm factors GATA4 ∼ 6 and how, if that exists, do these factors cooperate or compete with each other in the progression of hepatocellular carcinoma." (PMID 24498120, 2014). "However, whether GATA-2 and GATA-3 are involved in MICA/B expression in hepatoma cells is still unknown." (PMID 27528231, 2016).
lymphopenia (8 papers, 2016 to 2025). Reduction in the number of lymphocytes. "B- or NK cell lymphocytopenias may be present in GATA2 deficiency, and abnormal Ig levels may be present in GATA2 deficiency and TBD." (PMID 35356204, 2022). "Together with the observed lymphopenia (affecting CD4 T cells, B cells, and NK cells) and the presence of treatment-resistant warts on the patient's mother's hands, these immunological findings prompted us to sequence GATA2 in the patient and his mother." (PMID 30564229, 2018).
primary lymphedema (8 papers, 2013 to 2026). A congenital condition that results in swelling in the arms or legs, and can occur during adolescence or adulthood. "GATA2 is essential for lymphatic valve and vessel patterning, and its mutations cause primary lymphedema." (PMID 41562845, 2026). "Monoallelic missense mutations and intragenic microdeletions in human GATA2 cause Emberger syndrome, characterized by primary lymphedema with a predisposition to myelodysplastic syndrome or acute myeloid leukemia." (PMID 29035278, 2017). "Moreover, 2 recurrent mutations that cause reduced GATA2 expression (c.1017+512del28 and c.1017+572C>T) within a highly conserved 167-bp intragenic enhancer of intron 5 of GATA2 have been found in patients with primary lymphedema." (PMID 29035278, 2017).
pulmonary hypertension (8 papers, 2015 to 2025). Increased pressure within the pulmonary circulation due to lung or heart disorder. "Given the specificity of GATA2 expression in the pulmonary vasculature, we queried whether Gata2-deficiency might affect the severity of hypoxia-induced pulmonary arterial hypertension." (PMID 39739870, 2024). "GATA2 haploinsufficiency is also associated with pulmonary hypertension." (PMID 33802067, 2021). "Some GATA2 haploinsufficient patients develop pulmonary hypertension (PH), characterized by vascular remodeling and occlusion of small pulmonary arteries." (PMID 39739870, 2024). "Given the high expression levels of GATA2 in the pulmonary endothelial cells, we hypothesized that GATA2 is pathophysiologically involved in the response observed in the murine pulmonary hypertension (PH) model." (PMID 39739870, 2024). "Other mechanosensitive transcription factors and co-activators (e.g., TFII-I, GATA2, Twist1, YAP1) also control angiogenesis, and contribute to lung diseases (e.g., pulmonary fibrosis, pulmonary hypertension)." (PMID 30612120, 2019). "For example, mechanosensitive transcription factors (e.g., TFII-I, GATA2, TWIST1) control angiogenesis and EC integrity, and contribute to angiogenesis-related diseases (e.g., pulmonary fibrosis, pulmonary hypertension)." (PMID 31487690, 2019). "Other transcription factors and co-factors (e.g., TFII-I, GATA2, YAP1) that sense mechanical forces interact with Twist1, control angiogenesis, and contribute to age-related lung diseases (e.g., pulmonary fibrosis, pulmonary hypertension)." (PMID 33764901, 2021).
acute leukemia (7 papers, 2014 to 2025). A clonal (malignant) hematopoietic disorder with an acute onset, affecting the bone marrow and the peripheral blood. "In module 3, the results indicated that RUNX1, ZBTB16, GATA2 and MEIS1 which involved in the myeloid cell differentiation and the pathogenesis of acute leukemia showed higher levels of expression in cells from the MDS across differentiation." (PMID 38632656, 2024). "Driven by Ets-related protein 71 (ER71), GATA binding protein 2 (GATA-2), and stem cell leukaemia (SCL), haemangioblasts are able to differentiate into angioblasts and haematopoietic precursors." (PMID 30406137, 2018).